PDS5A (PDS5 cohesin associated factor A)
Description:
Probable regulator of sister chromatid cohesion in mitosis which may stabilize cohesin complex association with chromatin. May couple sister chromatid cohesion during mitosis to DNA replication. Cohesion ensures that chromosome partitioning is accurate in both meiotic and mitotic cells and plays an important role in DNA repair.
Synonyms: SCC-112; KIAA0648; PIG54; SCC112
Tractability: Antibody: its Gene Ontology location is reachable by antibodies, with high confidence. PROTAC: ubiquitination databases record sites on it; its protein half-life has been measured.
Gene: Protein-coding gene on chromosome 4 (39,822,863 to 39,977,987, reverse strand). Ensembl gene ENSG00000121892.
Subcellular location: Nucleus
Subcellular location (Human Protein Atlas): Nucleoplasm
Pathways (Reactome):
Cell Cycle: Cohesin Loading onto Chromatin; Establishment of Sister Chromatid Cohesion; Resolution of Sister Chromatid Cohesion; Separation of Sister Chromatids
Gene Ontology:
Molecular function: protein binding; cohesin unloader activity
Biological process: mitotic sister chromatid cohesion; negative regulation of DNA replication
Cellular component: chromatin; nucleoplasm; nucleus; chromosome; chromosome, centromeric region; cytosol
Genetic constraint (gnomAD): Loss-of-function variants: 13 observed, 39.71 expected, observed/expected ratio (o/e) 0.33, 90% interval 0.21 to 0.52. The upper end of that interval is the gene's LOEUF score, 0.52, which puts it in group 2 of 6, group 1 being the genes least tolerant of losing a copy. Missense variants: 366 observed, 537.48 expected, observed/expected ratio (o/e) 0.68, 90% interval 0.62 to 0.74. Synonymous variants: 204 observed, 199.71 expected, observed/expected ratio (o/e) 1.02, 90% interval 0.91 to 1.15.
Homologues: Orthologues: macaque PDS5A (99% identical), chimpanzee PDS5A (99% identical), pig PDS5A (99% identical), dog PDS5A (99% identical), rabbit PDS5A (99% identical), guinea pig PDS5A (98% identical), mouse Pds5a (98% identical), rat Pds5a (98% identical), tropical clawed frog pds5a (87% identical), zebrafish pds5a (81% identical), Drosophila melanogaster pds5 (34% identical), Caenorhabditis elegans evl-14 (22% identical). Paralogues in human: PDS5B (69% identical).
Diseases named in the same sentence as PDS5A in open-access papers:
PDS5A is named in the same sentence as 25 diseases in open-access papers, as found by Europe PMC text mining. Sharing a sentence is not in itself a finding about the gene and the disease. The quoted sentences say what the papers report.
acute myeloid leukemia (1 paper, 2022). Acute myeloid leukemia (AML) is a group of neoplasms arising from precursor cells committed to the myeloid cell-line differentiation. "For example, somatic mutations in the eight genes that comprise the cohesin ring (SMC1A, SMC3, STAG1, STAG2, RAD21) and the cohesin-ring support genes (NIPBL, MAU2, WAPL, PDS5A, PDS5B) and CTCF are frequently found in many cancer types and are especially common in acute myeloid leukemia (AML)." (PMID 36171609, 2022).
cervical carcinoma (1 paper, 2020). A carcinoma arising from either the exocervical squamous epithelium or the endocervical glandular epithelium. "First, we sought to determine the expression levels of the Pds5A and Pds5B proteins and their intracellular localization at specific stages of the cell cycle in a synchronized population of human cervical carcinoma cells (HeLa)." (PMID 32760717, 2020).
Cornelia de Lange syndrome (1 paper, 2020). A rare syndrome characterized by low birth weight, delayed growth, intellectual disabillity, behavioral problems, and a distinctive facial appearance (thin, arched eyebrows, low set ears, small teeth, and small nose). "Variants in genes encoding various structural or functional components of the cohesin complex, including RAD21, SMC1A, SMC3, BRD4, STAG1/2, NIPBL, HDAC8, WAPL, ANKRD11 and in single individuals PDS5A and ESPL1, have been implicated in Cornelia de Lange Syndrome (CdLS)." (PMID 32193685, 2020).
embryonal carcinoma (1 paper, 2022). A non-seminomatous malignant germ cell tumor characterized by the presence of large germ cells with abundant cytoplasm resembling epithelial cells, geographic necrosis, high mitotic activity, and pseudoglandular and pseudopapillary structures formation. "Mutations in ADAMTS20, ARHGAP10, OR1L4, PDS5A, and RPLP0 were only found in mixed germ cell tumors, while mutations in B3GNT8, CAPN7, FAT4, GRK1, TACC2 and TRAM1L1 were only observed in embryonal carcinoma, and their mutation frequency was around 2%." (PMID 36713456, 2022).
heart defects (1 paper, 2009). "Indeed, we found that Pds5A−/− mice, compared to wildtype mice, had significantly higher incidence of congenital heart defects (17/25 versus 3/18, P<0.001), including those that are commonly found in CdLS patients and Pds5B-deficient mice." (PMID 19412548, 2009).
heart failure (1 paper, 2009). Inability of the heart to pump blood at an adequate rate to meet tissue metabolic requirements. "While Pds5A−/− and Pds5B−/− mice die at birth, embryos harboring 3 mutant Pds5 alleles die between E11.5 and E12.5 most likely of heart failure, indicating that total Pds5 gene dosage is critical for normal development." (PMID 19412548, 2009).
liver neoplasm (1 paper, 2025). Tumors or cancers of the LIVER. "The ‘liver neoplasms’ CTD over-representation could be attributed to cell cycle-related pathway enrichment and corresponding genes (cell cycle: PDS5A, ORC6, RAD21, ZBTB17; Thyroid cancer: CTNNB1, RET) identified from our CRIPSR screens." (PMID 41446233, 2025).
malignant glioma (1 paper, 2016). A grade III or grade IV glioma arising from the central nervous system. "Altered expression levels of PDS5A have been observed in tumors of the breast, kidney, esophagus, stomach, liver and colon and in malignant gliomas." (PMID 27437769, 2016).
megacolon (1 paper, 2009). "In summary, we have discovered that PDS5B is mutated in a familial case of CdLS with megacolon, and that PDS5A and PDS5B have both redundant and distinct roles in development that are likely unrelated to its ancient function in sister chromatid cohesion." (PMID 19412548, 2009).
Tetralogy of Fallot (1 paper, 2009). A congenital cardiac malformation comprising pulmonary stenosis, overriding aorta, ventricular septum defect, and right ventricular hypertrophy. "For instance, we identified Pds5A heterozygotes with tetralogy of Fallot (TOF, a common malformation in CdLS, which was also associated with an ASD; 1/19), ASD alone (3/19), or VSD (1/19)." (PMID 19412548, 2009).
cancer (11 papers, 2014 to 2025). A tumor composed of atypical neoplastic, often pleomorphic cells that invade other tissues. "We also identified several cancer-related genes affected by SF3B1-associated abnormal splicing: NF1, PDS5A, DICER1, and PML." (PMID 30194306, 2018). "Similar to PCA, PDS5A deletion was detected in lower frequencies in 20% of cancer types." (PMID 31222142, 2019). "PDS5A may also play a critical role in initiation and development of cancer." (PMID 34070827, 2021).
tumor (5 papers, 2014 to 2025). "A study of the paired sets of human tumor and normal tissues revealed that the PDS5A mRNA and protein levels were significantly low in primary tumor tissues as compared to the corresponding normal breast and kidney tissues." (PMID 34070827, 2021). "PDS5A is reported to be up-regulated in esophagus, stomach, and liver tumors tested in each paired set of normal and tumor tissues." (PMID 34070827, 2021). "When a tumor lacks PDS5B, depletion of PDS5A is expected to inhibit the tumor’s growth, and vice versa." (PMID 34070827, 2021). "PDS5A is significantly overexpressed in human gliomas, and its overexpression is correlated positively with the tumor grade." (PMID 34070827, 2021). "Typical examples included known or putative tumor suppressors, such as NF1, DICER1, PML, PDS5A, MAP3K7, and PPP2R5A, in which SF3B1 mutation resulted in usage of alternative 3′ splice sites." (PMID 30194306, 2018). "Taken together, these data indicate that the presence of tumor-derived STAG2 mutations results in a decrease in levels of cohesin and a reduction in ability of WAPL, PDS5A, and PDS5B to interact with cohesin." (PMID 26871722, 2016). "The mechanism by which PDS5A overexpression promotes tumor growth remains to be revealed." (PMID 34070827, 2021).
PDS5A also shares sentences with these, for which no sentence is quoted: hepatocellular carcinoma (2 papers); acute myocardial infarction (1); breast carcinoma (1); cleft palate (1); Ewing sarcoma (1); malaria (1); melanoma (1); mixed germ cell tumor (1); myeloid malignancies (1); myopia (1); thyroid cancer (1); tumors of the breast (1); virus infection (1).